DHCR24 (24-dehydrocholesterol reductase)
Diseases named in the same sentence as DHCR24 in open-access papers (continued):
Sharing a sentence is not in itself a finding about the gene and the disease.
melanoma (continued). "Lipid metabolism genes such as fatty acid synthase (FASN) and 24-dehydrocholesterol reductase (DHCR24) have been proposed to contribute to tumor aggressiveness, but the therapeutic value of lipid metabolism inhibitors, particularly in drug-resistant melanoma, is unknown." (PMID 34068792, 2021). "At the same time, our data show that DHCR24 induces CYP27A1 expression and increases HMGCR and CYP27A1 expression in vemurafenib-resistant melanoma cell lines, suggesting an enhanced regulatory loop mechanism." (PMID 38775844, 2024). "As an example, simultaneous treatment of melanoma cell lines with FASN and DHCR24 inhibitors (PLX4032 and U1866A) increased number of apoptotic cells." (PMID 38672427, 2024). "Upregulation of additional genes from the bile acid and peroxisome signaling pathways was also evident in TIL gene and pathway expression analysis, including upregulation of SOD1, ACSL5, FADS2, CAT, DHCR24, SLC27A2, and IDH2 in melanoma TILs compared to pCD8s." (PMID 38023136, 2023). "More importantly, DHCR24 promotes the growth of CSC-like populations by activating the Hedgehog signaling pathway in breast cancer and protects melanoma cells from apoptosis, suggesting a possible role of DHCR24 or cholesterol in cancer metastasis and recurrence." (PMID 38775844, 2024). "Specifically, we showed that the combination of BRAFi with inhibitors of lipogenic enzymes fatty acid synthase (FASN) and 24-dehydrocholesterol reductase (DHCR24) resulted in favorable drug interactions, potentially exploitable for the treatment of BRAFi-resistant melanoma." (PMID 38338838, 2024). "Although DHCR24 is the final limiting enzyme of cholesterol synthesis, the catabolic fate of cholesterol in melanoma cells was not yet understood." (PMID 38775844, 2024).
breast carcinoma (7 papers, 2022 to 2025). "We then identified a key gene, DHCR24, which is involved in cholesterol production and is often found at high levels in breast cancer patients." (PMID 41514881, 2025). "Both ZMYND8 and DHCR24 promote breast cancer stem cell survival." (PMID 39757707, 2025). "Additionally, DHCR24 promotes the cell proliferation of cancer stem cells of breast cancer via regulation of Hedgehog pathway." (PMID 35197069, 2022).
atherosclerosis (6 papers, 2017 to 2025). A disease characterized by the build-up of fatty material and calcium deposition in the arterial wall resulting in partial or complete occlusion of the arterial lumen. "Inhibition of DHCR24 leads to accumulation of desmosterol, and depletion of desmosterol in myeloid cells by overexpression of DHCR24 promotes the progression of atherosclerosis." (PMID 36819785, 2023). "Some of the top canonical pathways identified at the proteome level (e.g., atherosclerosis signaling, LXR/RXR activation, DHCR24 signaling and production of NO) were also present at the phosphoproteome level, indicating their regulation by phosphorylation." (PMID 41441338, 2025). "Supporting this data, a knock-in mouse model with overexpression of Dhcr24, specifically in myeloid cells, showed downregulation of desmosterol, inactivation of LXR, and exacerbation of atherosclerosis." (PMID 39404366, 2024). "While the tendency in the global and phosphoproteomics was similar regarding NO production, it was the opposite with atherosclerosis signaling, LXR/RXR activation, DHCR24 signaling and IL-12 signaling, further highlighting the importance of phosphoproteomics in the study of obesity and T2D." (PMID 41441338, 2025). "Since DHCR24 inhibition by SH42 did not affect atherosclerosis in both mouse models, we next evaluated whether common genetic variants within the DHCR24 locus would associate with coronary artery disease (CAD) in humans using the largest dataset published to date." (PMID 38770137, 2024).
endometrial cancer (6 papers, 2017 to 2023). Primary or metastatic malignant neoplasm involving the endometrium (mucous membrane that lines the endometrial cavity). "DHCR24 was highly expressed in a tissue microarray with endometrial carcinoma of 258 patients, and the upregulation was associated with reduced overall survival." (PMID 35626014, 2022). "Knockdown of DHCR24 inhibited the metastatic ability of endometrial cancer cells and upregulated progesterone receptor expression." (PMID 36712880, 2022). "The previous study indicated a significant correlation between DHCR24 overexpression and aggressive tumor behaviors in endometrial cancer, such as cell invasion and migration." (PMID 36483599, 2022). "The data were in line with previous literature showing the important role of DHCR24 in tumor growth and metastasis, which also indicated that DHCR24 might become an effective target in endometrial cancer therapy." (PMID 36483599, 2022). "In this study, we found that an important factor, insulin, could induce the overexpression of DHCR24 in endometrial cancer cells, which agrees with the finding that hyperinsulinemia is quite prevalent in EC7." (PMID 28112250, 2017). "DHCR24 alteration is related to tumor progression and may serve as a novel prognostic factor and potential biomarker for endometrial cancer." (PMID 28112250, 2017). "DHCR24 could serve as a potential therapeutic target for the treatment of endometrial cancer." (PMID 36483599, 2022). "However, the function of DHCR24 in endometrial cancer (EC) remains largely elusive." (PMID 28112250, 2017).
hepatocellular carcinoma (6 papers, 2015 to 2023). A malignant tumor that arises from hepatocytes. "Suppression of DHCR24-mediated cholesterol biosynthesis and lipid rafts formation results in inhibition of tumor growth and invasion of hepatocellular carcinoma." (PMID 35197069, 2022). "In our previous study, we demonstrated that 3β-hydroxysterol Δ24-reductase (DHCR24) was overexpressed in hepatitis C virus (HCV)-related hepatocellular carcinoma (HCC), and that its expression was induced by HCV." (PMID 25875901, 2015). "In addition, a study showed that inhibiting the expression and activity of DHCR24, as well as cholesterol biosynthesis and the formation of lipid rafts mediated by DHCR24, can inhibit the invasion and migration of hepatocellular carcinomas." (PMID 36985615, 2023). "DHCR24-mediated cholesterol metabolism might be an effective therapeutic strategy in hepatocellular carcinomas (HCCs)." (PMID 35200397, 2022).
Obesity (5 papers, 2011 to 2025). Accumulation of substantial excess body fat. "Because obesity and lipid dysregulation are well-known hallmarks of type 2 diabetes, and because DHCR24 encodes for an enzyme related to the metabolism of cholesterol (3-hydroxysterol-24 reductase), an association between methylation at DHCR24 and type 2 diabetes is plausible." (PMID 37202507, 2023).
type 2 diabetes (5 papers, 2011 to 2025). "Four mQTL tagging the CpGs cg08857797 (VPS25), cg00144180 (HDAC4), cg16765088 (SYNM) and cg25536676 (DHCR24) were suggestively associated with type 2 diabetes, with an unadjusted GWAS p<0.05." (PMID 37202507, 2023). "Furthermore, CpGs annotated to ABCG1, DHCR24, and MYLIP were common to ischemic heart disease and type 2 diabetes." (PMID 37410739, 2023).
bladder cancer (4 papers, 2014 to 2024). "CDCA3, ANLN, STMN1, and DHCR24 play important roles in cell proliferation and migration of bladder cancer." (PMID 39540204, 2024). "DHCR24 promotes the proliferation of bladder cancer cells and bladder cancer patients have better clinical outcomes with lower DHCR24 expression in tumors." (PMID 35197069, 2022).
Cognitive impairment (4 papers, 2021 to 2024). Abnormal cognition is characterized by deficits in thinking, reasoning, or remembering. "The present study determined an underlying interaction of DHCR24 and hsa_circ_0015335 for cognitive impairment among CSVD patients." (PMID 39578712, 2024). "The study attempted to determine the underlying role and regulation mechanism of 3β‐hydroxysterol‐Δ24 reductase (DHCR24) in the pathophysiology of cerebral small vessel disease‐associated cognitive impairment (CSVD‐CI)." (PMID 39578712, 2024). "Thus, DHCR24 overexpression can alleviate cholesterol loss, reverse cognitive impairment, and prevent neuronal pathology, including amyloid‐β deposition, synaptic injuries, etc.." (PMID 39578712, 2024). "Notably, DHCR24 mutation or knockout leads to the loss of membrane cholesterol and disorder of lipid raft in the brain of patients and mice, resulting in synaptic abnormality and cognitive deficits." (PMID 37344916, 2023). "Surprisingly, by employing delivery of AAV9 carrying DHCR24 gene into the hippocampus of 5xFAD mice, we found that DHCR24 knock-in significantly reversed the cognitive impairment." (PMID 37344916, 2023). "Thus, DHCR24 is a pivotal factor influencing hsa_circ_0015335 on cognitive impairment in CSVD patients." (PMID 39578712, 2024). "In summary, our results identified that agomelatine could improve cognitive impairment and ameliorate AD-like pathology in APP/PS1 mice via activating DHCR24 signaling and inhibiting Akt/mTOR and Hes1/Notch1 signaling pathway." (PMID 35153715, 2021).
Infertility (4 papers, 2018 to 2023). "As example, the depletion of cholesterol in plasma and tissues in a mouse model deficient for the gene encoding 24-dehydrocholesterol reductase (Dhcr24) leads to mouse infertility." (PMID 30072948, 2018). "Moreover, cholesterol depletion in plasma and tissues in a mouse model deficient for the gene encoding 24-dehydrocholesterol reductase (Dhcr24) leads to mouse infertility." (PMID 37611828, 2023).
ovarian carcinoma (4 papers, 2018 to 2026). A malignant neoplasm originating from the surface ovarian epithelium. "DHCR24 contributes to ovarian cancer progression by upregulating the TGF-β1 pathway, highlighting its potential as a therapeutic target in ovarian cancer." (PMID 41050066, 2025).
dementia (3 papers, 2023 to 2024). Loss of intellectual abilities interfering with an individual's social and occupational functions. "Other NVU cell-type DEGs formed connections with both dementia and AD, including Plcg2 (microglia), Dhcr24 (astrocytes), and Psen1 (neurons)." (PMID 39456952, 2024).
hyperlipidemia (3 papers, 2020 to 2023). "We speculated that blocking the catalytic activity of DHCR24 could be a novel therapeutic strategy for treating hyperlipidemia." (PMID 36985615, 2023). "In conclusion, we show that pharmacological inhibition of DHCR24 increases desmosterol to prevent diet‐induced hepatic steatosis and inflammation, two main hallmarks of NAFLD/NASH development, without inducing hyperlipidemia." (PMID 37357756, 2023). "Importantly, DHCR24 inhibition by SH42 decreases plasma FFA and CE levels, without increasing plasma total TAG and DAG levels, which implies that LXRα activation by desmosterol, in contrast to synthetic agonists, does not lead to hyperlipidemia." (PMID 37357756, 2023).
ischemia (3 papers, 2017 to 2024). A hypoperfusion of the BLOOD through an organ or tissue caused by a PATHOLOGIC CONSTRICTION or obstruction of its BLOOD VESSELS, or an absence of BLOOD CIRCULATION. "The authors concluded that the DHCR24 enzyme has a neuroprotective role against cell death after ischemia, which was most likely through altered association of other proteins with the lipid rafts." (PMID 38672427, 2024). "Our data also showed the direct effect of loss of Dhcr24 in BM-Mono during hindlimb ischemia." (PMID 39404366, 2024). "However, further investigation is needed to dissect the causal effect of Dhcr24 regulation in monocytes during hindlimb ischemia, with particular emphasis on the translation of these findings for PAD/CLI in clinical settings." (PMID 39404366, 2024). "This study highlights that ischemia training reprograms BM-Mono in a positive way by downregulating their Dhcr24 expression and differentiating them towards less inflammatory M2-like macrophages, which are essential cells to improve outcomes in limb ischemia." (PMID 39404366, 2024). "This systemic effect is at least in part associated with circulating EVs that increase their HDAC1 cargo following ischemia training, leading to reprogramming of the BM-Mono by downregulating Dhcr24 gene expression in recipient cells." (PMID 39404366, 2024). "We also observed that the lentivirus-mediated overexpression of DHCR24 in striatum reduced the ischemia-induced lesion size in a mouse model of transient focal ischemia." (PMID 29115990, 2017). "Our recent data have demonstrated that ischemia training can reprogram BM-Mono, changing their lipid profile with downregulation of Dhcr24 and accumulation of desmosterol, leading to an improvement in limb perfusion and neovascularization in a mouse model of hindlimb ischemia." (PMID 39404366, 2024). "Collectively, these data suggest that the overexpression of DHCR24 is able to significantly, yet locally, mitigate the ischemia-induced damage in a mouse model of transient focal cerebral ischemia without significantly affecting the inflammatory, neurotrophic or oxidative stress responses." (PMID 29115990, 2017).
steatosis (3 papers, 2016 to 2024). Increased lipid within the cytoplasm of cells. "The second gene that may partner with HMGCR in reducing liver exposure to steatosis resulting from a high cholesterol supply is DHCR24." (PMID 39683393, 2024). "Thus, the HCV-induced oxidative stress responsive protein DHCR24 may play a critical role in the pathogenesis of not only HCV persistent infection, but also associated liver diseases as steatosis, steatohepatitis, and cirrhosis." (PMID 27293514, 2016).
adrenal carcinoma (2 papers, 2010 to 2023). A carcinoma involving a adrenal gland. "Additionally, reduced DHCR24 expression occurs in the temporal cortex of AD patients, and overexpression has been observed in adrenal gland cancer cells." (PMID 38239854, 2023).
cataract (2 papers, 2016 to 2023). Partial or complete opacity of the crystalline lens of one or both eyes that decreases visual acuity and eventually results in blindness. "Eisai identified DHCR24 as being involved in the development of cataracts in animals." (PMID 27572246, 2016). "Triparanol is the most widely used (nonspecific) DHCR24 inhibitor; however, it was withdrawn from clinical application due to severe adverse side effects, such as nausea and vomiting, cataracts, and skin disorders." (PMID 37357756, 2023).
colorectal cancer (2 papers, 2024). A primary or metastatic malignant neoplasm that affects the colon or rectum. "TASINs were found to inhibit EBP, DHCR7, and DHCR24, leading to colorectal cancer cell death." (PMID 38672427, 2024). "24-dehydrocholesterol reductase (DHCR24) is an important regulatory enzyme in cholesterol synthesis and has been documented as a ROS scavenger in colorectal cancer." (PMID 39830660, 2024).
diabetes (2 papers, 2017 to 2022). "Nevertheless, DHCR24 activity is also obviously downregulated by major risk factors from AD, such as aging, diabetes-related factors, amyloid-β (Aβ), oxidative stress, chronic inflammation, and genetic factors." (PMID 35296367, 2022).
glioma (2 papers, 2023). A benign or malignant brain and spinal cord tumor that arises from glial cells (astrocytes, oligodendrocytes, ependymal cells). "Interestingly, vitamin D3 obtained more significant inhibitory effects on cell viability and cell proliferation of patient‐derived glioma cell lines by inhibiting the expression levels of DHCR7 and DHCR24, thereby inhibiting cholesterol synthesis and cholesterol homeostasis pathways." (PMID 37489660, 2023).
Hepatic steatosis (2 papers, 2023 to 2025). Steatosis is a term used to denote lipid accumulation within hepatocytes. "Along these lines, it was recently found that inhibition of DHCR24 elevates desmosterol levels, thereby improving hepatic steatosis and inflammation." (PMID 40545240, 2025). "We show that inhibition of DHCR24 induces marked increases in desmosterol levels in both liver and circulation, which is accompanied by decreased hepatic steatosis and inflammation." (PMID 37357756, 2023). "Taken together, these data show that inhibition of DHCR24 by SH42 does not prevent diet‐induced hepatic steatosis and inflammation in LXRα‐deficient mice." (PMID 37357756, 2023). "Importantly, we observed that inhibition of DHCR24 by SH42 prevented high‐fat diet‐induced hepatic steatosis in E3L.CETP mice but not in LXRα‐deficient mice." (PMID 37357756, 2023). "In this study, we exploited the synthetic DHCR24 inhibitor SH42, developed by our group, for the treatment of hepatic steatosis and inflammation, that is, the two hallmarks of NAFLD/NASH development." (PMID 37357756, 2023). "Taken together, inhibition of DHCR24 by SH42 markedly increases liver desmosterol levels, accompanied by amelioration of diet‐induced hepatic steatosis without marked effects on body composition and glucose homeostasis." (PMID 37357756, 2023).
liver cancer (2 papers, 2022 to 2023). An epithelial or non-epithelial malignant neoplasm that arises from the liver. "Therefore, targeting DHCR24-mediated cholesterol metabolism may be an effective treatment strategy for liver cancer." (PMID 36985615, 2023). "Moreover, high expression of cholesterol synthesis enzyme 3β-hydroxysteroid-Δ24 reductase (DHCR24) has been found in human HCC liver, whereas inhibiting DHCR24 impeded tumor growth, invasion, and metastasis both in liver cancer cell lines and in Hep3B xenografts." (PMID 36712976, 2022).
liver disease (2 papers, 2016 to 2024). "The role of DHCR24 in HCV-associated liver diseases lies in its aberrant expression altering programmed cell death pathways." (PMID 27293514, 2016). "Δ24-Dehydrocholesterol reductase (DHCR24) converts desmosterol into cholesterol, and we previously showed that the DHCR24 inhibitor SH42 increases desmosterol to activate LXR and attenuate experimental peritonitis and metabolic dysfunction-associated steatotic liver disease." (PMID 38770137, 2024).
lung adenocarcinoma (2 papers, 2022 to 2023). A carcinoma that arises from the lung and is characterized by the presence of malignant glandular epithelial cells. "Furthermore, CRABP2, DHCR24, and AK4 are useful IHC markers for diagnosis of lung adenocarcinoma invasiveness and may be associated with malignant progression of AIS." (PMID 37004157, 2023). "Additionally, high expression of SRSF3 and DHCR24 was detected in other types of cancers, such as uterine corpus endometrial carcinoma and lung adenocarcinoma, suggesting that further investigations are required on the antitumor effects and underlying mechanisms of SFI003 in these cancers." (PMID 35501301, 2022). "Expression of CRABP2, DHCR24, and AK4, and clinicopathological features in patients with lung adenocarcinoma." (PMID 37004157, 2023).
lung carcinoma (2 papers, 2017 to 2022). "This extract has a strong antioxidant and repairing activity in the human lung cancer cell line (A549) as shown by the increased expression of dehydrocholesterol reductase-24 (DHCR24) and prostaglandin reductase 1 (PTGR1) genes and proteins." (PMID 28117410, 2017).